TNF (tumor necrosis factor)
Diseases named in the same sentence as TNF in open-access papers (continued):
Sharing a sentence is not in itself a finding about the gene and the disease.
tumor (continued). "Moreover, iv injection of TNF-α into the tail vein slightly upregulated NF-κB target genes (compared with the published articles), NFKBIA, and TNFAIP3, which were observed to examine the effect of TNF-α on the tumor NF-κB activity." (PMID 36110523, 2022). "Moreover, the strain also polarized macrophages to anti-tumor M1 phenotype, enriched Th1 cells population with high production of TNF-α, and decreased expression of IL-10, thus exhibiting enhanced therapeutic effects in a combined chemo-immunotherapy manner." (PMID 35757741, 2022). "These dual opposite effects of TNF-α may be due to the carcinogenic factors, histologic types of primary tumors, and the local tumor microenvironments, but the detailed mechanisms are still unclear." (PMID 36358977, 2022). "Inhibited the expression of PPP2CA, which could promote the release of pro-inflammatory cytokines such as IL-1b, IL-6, and TNF-a from macrophages stimulating tumor invasion." (PMID 36612080, 2022). "Furthermore, the antibody–cytokine fusion protein Daromun is a combined molecule consisting of IL-2 and TNF fused to the monoclonal antibody L19, which is specific to the alternatively spliced extra-domain B of fibronectin, a marker of tumor angiogenesis." (PMID 35158808, 2022). "However, we found a clear correlation between serum concentrations of chemerin and α-defensin 1 and salivary concentrations of TNF-α and the tumor grade (p < 0.05)." (PMID 36005576, 2022). "Interestingly, this corresponded to increased expression of TNF-α by Ly6C+ tumor-residing monocytes with a concomitant rise of serological TNF-α levels upon anti-PD-L1-treatment in vivo." (PMID 35493461, 2022). "Moreover, the B2 CAR T-cells elaborated greater IL-2, IFN-γ, and TNF-α compared to B1 during long-term exposure to tumor cells." (PMID 35222421, 2022). "In the GBM TME, TNF-α secretion stimulates tumor development and angiogenesis." (PMID 35054779, 2022). "Several successive investigations conducted in 1980 on BCG-infected mice showed the capacity to induce the release into the serum of a substance named tumor necrosis factor, TNF, which mimicked the tumor-necrotizing action of endotoxin and was inhibitory or cytotoxic to a range of tumor cell lines." (PMID 35873564, 2022). "This also demonstrates an advantage of this strategy of using autologous MCs as anti-tumor cells since anti-tumor mediators, such as TNF-α, can be targeted and released through a tightly controlled mechanism such that the molecules are delivered specifically within the tumor cells." (PMID 35740607, 2022). "Under these conditions only TNF-α showed a pro-apoptotic function on LL/2 tumor cells." (PMID 35514957, 2022). "Furthermore, we observed a correlation between the levels of IFN-γ and the TNFα level in tumor tissues (p < 0.0001)." (PMID 35056404, 2022). "The frequencies of CD4+IFN-γ+TNF-α− and CD8+IL-10+ T cells showed the most positive associations with the parameters known to be indicators of a poor prognosis such as LNs involvement, larger tumor size and higher stage of the disease." (PMID 36376825, 2022). "Moreover, existing evidence has shown that hypoxia-associated inflammatory cytokines or chemokines were significantly elevated in the tumor microenvironment, for example, IL-6, IL-1, and TNF." (PMID 35309351, 2022). "The SMAC-lacking tumor showed reduced expression of inflammation-related proteins such as NF-kB and TNF-α, and of the PD-L1, associated with immune system suppression." (PMID 36185255, 2022). "Moreover, TNF-α can enhance phagocytic effects of macrophages to kill exogenous pathogens or inhibit tumor cells." (PMID 36071932, 2022). "Moreover, TNF contributed to a more homogenous drug distribution, so that a larger tumor area took up a greater therapeutic concentration of DXR." (PMID 36297598, 2022).
tumor (continued). "In this Review, we provide an updated overview of the molecular mechanisms regulating cell fate decisions in tumor cells undergoing ER stress and discuss the role of the tumor necrosis factor (TNF)-related apoptosis-inducing ligand receptor 2 (TRAIL-R2/DR5) in the final outcome of UPR signaling." (PMID 36012252, 2022). "The survival curvesof this experimental group correlated well with the tumor growth results.In addition, the serum levels of cytokines such as TNF-α andIFN-γ in this experimental group were found to be much higherafter the rechallenge with 4T1 tumor cells for 6 days." (PMID 35926215, 2022). "In addition to VEGF, TAMs also secrete a variety of cytokines in tumors, such as PDGF, IL-8, TNF-α and basic fibroblast growth factor, which further promote tumor invasion and metastasis." (PMID 36611857, 2022). "Regarding the ADP@SWNT/TNFα group, the tumor structure was partially damaged, and cell necrosis could be found." (PMID 34994069, 2022). "TNF-α is also a multi-functional cytokine, which plays an important role in immune regulation and inflammatory response, and can participate in the regulation of tumor cell apoptosis, proliferation, angiogenesis, differentiation, and migration." (PMID 36212428, 2022). "Interestingly, SERPINA3 was positively correlated with TNF and TNF was positively correlated with CCL2, a marker of tumor associated macrophages." (PMID 36406134, 2022). "Inflammatory cytokines, including tumor necrosis factor-alpha (TNF-α) and IL-1b, can influence the expression of transcription factors that induce epithelial to mesenchymal transitions, which enable the dissemination of tumor cells." (PMID 36140220, 2022). "Key features of cancer-related inflammation are infiltration of white blood cells, tumor-associated macrophages (TAM), cytokines, such as IL-1, IL-6, and TNF-α, some chemokines, cell cycle acceleration, cell proliferation, evasion from apoptosis, and stimulation of tumor angiogenesis." (PMID 35163356, 2022). "Compared with the control and Lmo treatments, the tumor‐bearing mice treated with Lmo@RBC displayed an obviously high level of IL‐6, IL‐1β, and TNF‐α in blood serum, which was attributed to the high‐efficiency tumor‐homing capability of Lmo@RBC to improve the therapeutic efficiency." (PMID 36266982, 2022). "KEGG assays revealed MMP12 may influence the activity of several tumor-related pathways, such as the Toll-like receptor signaling pathway, TNF signaling pathway, and IL-17 signaling pathway." (PMID 35265129, 2022). "The anti-tumor effect was related to a higher expression of TNF-α and IL-10 in the bladder." (PMID 35214691, 2022). "Inhibition of the NFκB pathway might be a useful target to sensitize tumor cells to TNFα-induced-apoptosis." (PMID 35723290, 2022). "CD8+ T cells exert their antitumor function both directly, by killing tumor cells expressing tumor-associated antigens on MHC-I molecules, and indirectly, by releasing proinflammatory cytokines (such as IFN-γ and TNF-α) that activate other leukocytes and sustain their antitumor activities." (PMID 35874810, 2022). "TNF-α promotes tumor formation by modulating the release of metalloproteinase and possesses angiogenic activities, which may be essential for cancer invasion and metastasis." (PMID 36140470, 2022). "SREBPs are essential to maintain Treg viability and immunosuppression in the TME, as SCAP deletion to inhibit the expression of SREBP target genes increased the frequency of IFN-γ+ Tregs in the tumor while also increasing the number of TNF-α- and IFN-γ+ polyfunctional CD8 T cells." (PMID 34983949, 2022). "However, other sources of TNF-α were shown to include white blood cells, mesangial cells, fibroblasts, astrocytes, Kupffer cells, smooth muscle cells, keratinocytes, tumor cells, and adipocytes." (PMID 35406450, 2022).
tumor (continued). "In addition, GSEA concluded that MS4As were involved in several tumor-related pathways, including TNF-α via NF-kB signaling, IL6/JAK/STAT3 signaling, IFN- γ response, IFN-α response, and epithelial–mesenchymal transition (EMT)." (PMID 35734424, 2022). "Interestingly, TNF-α is an abundant cytokine in PDA TME, yet the role of TNF-α in tumor development remains paradoxical and has been shown to be antitumor and protumor in different contexts." (PMID 36256464, 2022). "TNF-α could be either pro- or anti-tumorigenic, stimulating cancer cell growth, proliferation, invasion, and tumor angiogenesis, or kill cancer cells." (PMID 35883451, 2022). "Surprisingly, tumor oxygenation increased one day after TNF injection." (PMID 36551505, 2022). "Both T cells and CAR-T20 cells resulted in a slight increase in murine TNF levels, while tumor burden, T cells and CAR-T20 cells could also introduce a mild increase in murine IL-6." (PMID 36352168, 2022). "Cytokines such as tumor necrosis factor (TNF)-α, interleukins, and transforming growth factor(TGF)-β, which are produced by tumor cells and surrounding cells including cancer-associated fibroblasts stimulate a epithelial-mesenchymal transition to promote cancer progression, invasion, and metastasis." (PMID 35538112, 2022). "Tumor-associated macrophages are a primary source of anti-inflammatory molecules such as TGF-β, ARG1, and IL-10, as well as pro-inflammatory molecules such as tumor necrosis factor-α (TNF-α), IL1-β and CXCL10." (PMID 36276147, 2022). "Many molecular pathways of TNF-alpha are associated with the upregulation of matrix metallopeptidase 9 [MMP9] which directly degrades the extracellular matrix allowing tumor migration and indirectly promotes cytokines that support cell tumor growth." (PMID 36672607, 2022). "Meanwhile, CD3+, CD4+, and TNFα levels might be valuable immune indicators of tumor response, and should be paid more clinical attention." (PMID 36158692, 2022). "Our data add new evidence for the tumor-promoting role of TNF-α." (PMID 35725556, 2022). "iNKT cells exert anti-tumor effector cell activities by producing several Th1 cytokines, i.e. IFNγ, TNFα, and by eliminating CD1d-expressing tumor cells, thus they represent a potential intriguing therapeutic cellular tool against cancer development and metastasis." (PMID 36338516, 2022). "M1 macrophages play an anti-tumor role by activating the immune system and releasing tumor necrosis factor, nitric oxide, and reactive oxygen species, while macrophages M2 is the main participant and coordinator in promoting tumor progression in the tumor microenvironment." (PMID 35281077, 2022). "The M1 activation induced by lipopolysaccharide (LPS) or cytokines such as interferon-gamma (IFN-γ) and tumor necrosis factor-alpha (TNF-α), is characterized by high antigen presentation capacity, the killing of intracellular pathogens, secretion of pro-inflammatory cytokines and anti-tumor effects." (PMID 35625939, 2022). "Furthermore, PD‐L1 expression is enhanced by TNF‐α and IL‐1β, suggesting that the expression of PD‐L1 in tumor cells changes depending on the tumor microenvironment." (PMID 34842351, 2022). "We also assessed whether the levels of RANTES, TNFα, IFNγ, TGF- β1, PD-L1, VEGF-A, and VEGF-C were associated with some histopathological parameters: MVD (microvessel density), budding, and tumor-infiltrating lymphocytes." (PMID 35208526, 2022). "However, TNF-α levels showed no changes in all treatment groups, indicating that SXT-mediated tumor necrosis is involved in TNF-α regulation." (PMID 35372052, 2022). "TNF-α stimulates the early phase of the inflammatory response and regulates the production of other cytokines, increasing vascular permeability, and enhancing oncogene activation, angiogenesis, tumor cell invasion, and migration." (PMID 35884974, 2022). "Although TNF-α is called tumor necrosis factor, it can also promote tumor development." (PMID 36358977, 2022).
tumor (continued). "Notably, nano-gold-loaded TNF generate better anti-tumor activity and lower adverse reactions at lower doses compared to free TNF." (PMID 35664731, 2022). "In NSCLC tissues, high expression of NR2F6 was detected in tumor-infiltrating lymphocytes (TILs), and upregulated NR2F6 expression was associated with impaired production of cytokines, including IL-2, TNF-α, and IFN-γ,185 suggesting that NR2F6 on TILs contributes to tumor immunosuppression." (PMID 36123348, 2022). "The activation of the complement system has become a mediator in anti-tumor treatment, which also increases the secondary inflammatory mediators, such as cytokines IL-1β, IL-6, IL-10, TNF-α, and G-CSF, leukotrienes, thromboxane, prostaglandins, histamine, and coagulation factors." (PMID 35692783, 2022). "It has been reported that soluble TNFR2, which is highly secreted by Tregs in the tumor microenvironment, can bind to membrane TNF on tumor cells to form a reverse transduction signaling pathway to induce the NF-κB pathway, thereby promoting the survival of lymphoma cells." (PMID 35494080, 2022). "Although previous studies hinted the possible involvement of WBP2 in inflammation, via its binding to ITCH, a negative regulator of TNF/NF‐κB signaling, this study shows for the first time a participatory role of WBP2 in tumor inflammatory signaling, particularly in TNF/NF‐κB signaling pathway." (PMID 34197030, 2022). "Notably, tumor-infiltrating Tregs showed increased TNF-α production in the NEO cohort compared with the PR cohort." (PMID 36509285, 2022). "Furthermore, ADAM17 is able to promote tumor growth via induction of inflammatory processes, such as TNF α signaling and interleukin 6 (IL-6) trans-signaling." (PMID 36078095, 2022). "Reduced levels of anti-inflammatory cytokines (such as adiponectin) and increased levels of proinflammatory cytokines (such as tumor necrosis factor α (TNFα), interleukin (IL)-1β, IL-6, and IL-8), which can have mitogenic, anti-apoptotic, and angiogenic effects, accelerate tumor progression." (PMID 35145826, 2022). "It was also reported that increased tumor-infiltrating mast cells could foster immune suppression and GC progression through TNF-α-PD-L1 pathway." (PMID 35273959, 2022). "However, YS49 and TNFα converted skeletal host cells such as MSCs and chondrocytes into iTSCs and iISCs, and they generated tumor-suppressive and inflammation-suppressive CMs." (PMID 35804814, 2022). "As we know, IL-1β and TNF-α are important in the tumor microenvironment." (PMID 36016583, 2022). "Nevertheless, it seems that a more significant anti-tumour effect was achieved by the use of pro-inflammatory cytokines in combination with anti-PD1/PDL1 antibodies, such as demonstrated for IL-12 and IL-2 with TNFα encoding virus vectors." (PMID 36140243, 2022). "When TNF-α plays a tumor promoter role, a TNF-α inhibitor can be an attractive targeted treatment." (PMID 36140220, 2022). "In vitro and in vivo studies showed that these NP could reprogram M2 to M1 MP producing high levels of NO and TNF, leading to synergistic tumor therapy." (PMID 35163420, 2022). "The activated NK cells may serve as anti-tumor therapy by secreting IFN-γ and TNF-α to suppress tumor cell cycle." (PMID 35488327, 2022). "Similarly, B1a Bregs (CD19+CD5+CD43+) have been described to use IL-10 to inhibit IFNγ and TNFα production by CD8+T cells thus negatively regulating tumour immunity against melanoma cells." (PMID 35350071, 2022). "Due to its similar effects of LT-α on tumor cells to TNF-α, it was renamed TNF-β in 1985." (PMID 35057080, 2022). "Crocin is likely to exert an anti-tumor activity through downregulation of TNF-α and NF-κB." (PMID 36139719, 2022). "Both TNF and IL-6 represent so called “acute phase proteins” that stimulate the liver to produce and secrete other inflammatory ligands that trigger both general and tumor-type-specific carcinogenic effects." (PMID 35205678, 2022).
tumor (continued). "Furthermore, tumor infiltrating CD8+ T cells in GABA-treated mice showed downregulation of tumor necrosis factor (TNF) target gene transcripts." (PMID 35915062, 2022). "The activity of CTLs could be enhanced when co-cultured with CMTM6 depletion tumor cells, mainly manifested by increased secretion of perforin, TNF-α, IFN-γ and IL-2." (PMID 35958549, 2022). "The correlation between these molecules may indicate the participation of TNFα in the regulation of periostin levels in the tumor microenvironment." (PMID 35056404, 2022). "In the inflammatory tumor microenvironment (TME), innate immune cells such as monocytes and adaptive immune cells (e.g., T lymphocytes) directly contact or produce a variety of inflammatory mediators [e.g., tumor necrosis factor (TNF), IL-6] in response to aberrant signals from the tumor." (PMID 36313280, 2022). "As a master regulator of inflammation, NFκB may not only regulate TNF-mediated cell fate decisions, but also whether dying tumor cells evoke immunogenicity." (PMID 35625711, 2022). "TNF-α is recognized as one of the major mediators of cancer-related inflammation, mediating all steps of tumorigenesis, such as proliferation, invasion, angiogenesis, and metastasis formation by accelerating tumor invasion and metastasis through EMT." (PMID 35454852, 2022). "WAP can enhance phagocytosis by macrophages, while ALP enhances the activation of lymphocytes to increase the release of cytokines such as interleukin -2 (IL-2), interleukin -12 (IL-12), interferon-gamma (IFN-γ) and TNF-α, which together induce the necrosis and apoptosis of tumor cells." (PMID 36278230, 2022). "TNF-α is a cytokine produced mainly by macrophages and tumor cells." (PMID 36005576, 2022). "Besides, RuPOP@CM can enhance the activity of cellular immune response and promote the production of inflammatory cytokines including TNF-α, IL-12 and IL-6, which is of great significance in treatment of tumor." (PMID 36064356, 2022). "Importantly, U87 cells treated with g82/165 + HDR polarized tumor-associated macrophages (TAM) toward an M1 phenotype, as indicated by an increase in TNF-α and a decrease in IL-4 secretions." (PMID 35165339, 2022). "For instance, TNFα and IL-1 are cytokines secreted from tumor cells that can induce NF-κB." (PMID 36078078, 2022). "Finally, the clinical efficacy, immunoglobulin, serum tumor markers, and serum TNF-α of the two groups were compared." (PMID 35035510, 2022). "This indicates that whilst TNFα and IL-1 signaling were significantly enriched in 5-FU chemo-immunotherapy treated tumors, the robust anti-tumor response produced by this additive chemo-immunotherapy is likely to be dependent on the combination of multiple molecular pathways." (PMID 35634282, 2022). "Addition of low dose TNF specifically stimulated the permeability of the tumor-associated vasculature for liposomes, whereas no increased DXR distribution was observed in the vital organs." (PMID 36297598, 2022). "CD8 + T cells directly contributed to tumor eradication through the secretion of perforin, granzyme, and TNF or through their binding to Fas-FasL in tumor tissues, and their expansion may help patients live longer." (PMID 35991574, 2022). "The DCs are created via isolation of monocytes from patient sera, then stimulation with IL-4, GM-CSF, then TNF-α, and finally by adding the peptides (derived from autologous tumor lysate or synthetically produced) to the DCs in a pulsed fashion to improve antigen presentation." (PMID 35690784, 2022). "IFN-γ and TNF-α are secreted to induce tumor cells cytotoxicity." (PMID 35874717, 2022). "The administration of type 2 diabetes drug metformin to an osteosarcoma mouse model was also shown to inhibit tumor growth associated with an increase of production of IL12 and TNF by TAM, and an elevation of MHC class II and a reduction of CD206 expression by TAM." (PMID 35163420, 2022).